CD4 (CD4 molecule)
Diseases named in the same sentence as CD4 in open-access papers (continued):
Sharing a sentence is not in itself a finding about the gene and the disease.
infection (continued). "The response induced by cps1-1 is marked by local production of IL-12 and IFN-γ, along with the occurrence of antigen-specific CD8+ T cells that appear rapidly following infection in partial dependence upon CD4+ T lymphocytes." (PMID 39440975, 2024). "A few studies have assessed vaccine candidates eliciting CD8 + and/or CD4 + T cells that correlate with protection from liver-stage infection in mice and one clinical trial, but the mechanism that leads to T cell protection remains to be elucidated." (PMID 38783317, 2024). "First, we wanted to know what ape CD4 was like before SIVs spilled over to apes and began to exert infection pressure on them." (PMID 38014262, 2024). "While productive infection of dendritic cells is less common and less efficient than infection of CD4+ T cells, DCs provide an effective transmission route to T cells via “trans-infection”, preferentially to activated CD4+ T cells." (PMID 39205255, 2024). "In contrast, CD4 cell depletion (day −1) did not affect the numbers of Her2+ cells at 9 dpi, consistent with the delayed accumulation of CD4 cells late during the infection." (PMID 38645169, 2024). "We had access to cells collected before and post-infection, which enabled detailed studies to be conducted of CD4+ and CD8+ T cell responses to TBEV-infection in the patient." (PMID 38676861, 2024). "ART allows for the restoration of peripheral CD4 + T cell populations, but memory CD4 + T cells are often depleted early in infection." (PMID 39609320, 2024). "In both young and aged animals, a large influx of CD4 T cells was detected early, and their levels remained elevated throughout the course of infection in both lungs, in line with the reported role of CD4 T cells in fighting mycobacteria." (PMID 38771046, 2024). "aureus infection, we discovered that the breadth of bacterium-specific memory CD4+ T-cell pool is a critical factor for protective immunity against invasive S." (PMID 38868766, 2024). "Prior studies using murine models using different Ehrlichia species pathogens reported that CD4+ T cell-mediated IFNγ production is essential for mitigating a fatal outcome from an infection." (PMID 39204029, 2024). "The frequency of CD4+IFN-γ+ T cells, CD8+IFN-γ+ T cells, and CD4+IL-4+ T cells in the dLNs and at the site of infection of Gsdmd-/- and C57BL/6 control mice remained unchanged, as determined by flow cytometry." (PMID 39250503, 2024). "Our results are consistent with persistent expanded CD4+ T cell clones harboring proviruses that can be established early in infection and can contribute to persistent residual viremia on fully suppressive ART." (PMID 38593120, 2024). "An adaptive immune response relying on CD4 T cells is crucial for effective infection management, as F11 dependent neutralization alone is insufficient for survival." (PMID 39599888, 2024). "Patients with gB4 glycoprotein infection had a significantly lower CD4+/CD8+ ratio at D90 (p < 0.026)." (PMID 38675390, 2024). "Mechanistically, we show that HTLV-1–infected DP T cell populations are generated by infection of SP CD4+ and CD8+ T cells." (PMID 38193535, 2024). "This is further exacerbated by the establishment of functionally quiescent infection of self-renewing CD4+ T memory cells that coordinate immune response to infection." (PMID 38216975, 2024). "Especially noteworthy is the markedly elevated probability of pulmonary polymicrobial infections among individuals with CD4+T cell counts <50/μl compared to those with CD4+T cell counts >200/μl." (PMID 38774626, 2024). "In contrast, IL-27 secreted by B cells was relevant at later phase of the infection and facilitated maintenance and function of virus-specific CD4 T cells as well as CD4 TFH function, which promoted humoral immunity and viral clearance." (PMID 38966644, 2024).
infection (continued). "PBMCs, treated with varying concentrations of bNAbs, were inoculated with either control or semen-exposed virus, and again, infection rates were determined by p24 staining in CD4 target cells." (PMID 38501840, 2024). "Comparative data analysis of naïve C57BL/6 splenocytes and cells derived from 14- and 42 days post infection allowed to characterize six CD4+ T cell subpopulations affected by experimental T. (b)." (PMID 38535532, 2024). "Among PLWH, HIV-RNA was <50 copies/mL in 44 (89.8%), and the median CD4+ T lymphocyte count was 690 cells/microL (IQR = 559–1005) at the time of mpox infection." (PMID 38793563, 2024). "There was a 3-fold defect in the frequency of CD69/CD103 double-positive cells among S- and N-specific CD4 T cells in the BAL at 4–5 weeks post-infection in the anti-IL-10 treatment group relative to controls." (PMID 38950078, 2024). "CD4+ T cell activation in response to the MP BA.2 subvariant was increased between pre-immune timepoint and 2 to 8 weeks post-infection (p<0.01) and between 2nd dose + 4 weeks and 2 to 8 weeks post-infection (p<0.001)." (PMID 38812507, 2024). "In patients with three vaccine doses, CD4 T cell frequencies were 0.079% (0.034–0.167) before and 0.090% (0.028–0.122) after infection; CD8 T cell frequencies were 0.021% (0.004–0.079) vs. 0.061 (0.025–0.108)." (PMID 39260039, 2024). "During MmuPV1 infection, antibody-based depletion or genetic deletion of CD4+, CD8+, and CD3+ T cells significantly increases papilloma formation and SCC development, indicating that T cells can restrict papillomavirus-induced disease progression." (PMID 38793562, 2024). "The expression of PD-1 and TIGIT on CD4+ T cells at 2-4 weeks post-infection were variable and uncorrelated with adaptive immunity." (PMID 39355257, 2024). "Instead, memory lymphocyte clusters, consisting of CD4 T and B/plasma cells, have been observed in murine uterine tissue months after the infection resolves." (PMID 39043447, 2024). "Twelve weeks post-infection, these mice exhibited autoimmune characteristics, including stomach inflammation characterized by the production of autoantibodies and autoreactive CD4+ T cells." (PMID 38571951, 2024). "The DRB1*16 allele was associated with past infection, anti-VCA IgG titer regulation and a high CD4(+) T lymphocyte count but was suggestive of a low CD8(+) T-cell count." (PMID 38933108, 2024). "Its p protein inhibits interferon-I production, while CD4+ T lymphocyte activation is compromised during infection." (PMID 38674586, 2024). "During adaptive immune responses to infection, naive CD4+ T cells differentiate into T helper subsets with distinct effector functions." (PMID 39560988, 2024). "Analysis of the T cell response over time revealed that like CD8+ T cells, CD4+ T cells from memory mice readily produced IFN-γ as early as 2 d post infection, which declined again thereafter." (PMID 38838013, 2024). "Reservoir size has also been shown to be inversely correlated to the nadir CD4 count, likely a proxy for longer duration of infection." (PMID 39345793, 2024). "In stark contrast, modern chimpanzee and gorilla CD4 orthologs are less supportive of infection by these viruses, consistent with natural selection having shaped CD4 to resist infection in these species." (PMID 38014262, 2024). "Expression of CD27, which is downregulated in some HCMV-specific CD4 T cells during latency, was largely similar to that of naive CD4 T cells at day 8 of infection." (PMID 38236791, 2024). "We observed a significant activation response of CD4+ T cells against MP-R and MP-BA.2 at the 2nd dose + 4 weeks and 2 to 8 weeks post-infection visit, compared to the pre-immune visit." (PMID 38812507, 2024). "While pDCs attract CD4 T cells to the site of infection via their pro-inflammatory chemokines (CCL3-5), they also inhibit HIV entry as these chemokines bind to CCR5 and with their IFN production, they inhibit viral spread." (PMID 38924030, 2024).
infection (continued). "Re-exposure to pneumococcus 1 week after initial infection stimulates the CD4+ cell-dependent accumulation of activated, proliferative EV B cells in a manner that is independent of CD40L and CXCL13." (PMID 38715601, 2024). "In this study, we sought to evaluate long-lived immunological reprogramming in pulmonary granulomas after primary and secondary infection and to elucidate the role of CD4+ T cells in protection against reinfection." (PMID 39214090, 2024). "Clearly, prolonged infection and chronicity in CD4+ depleted and CD40L blocked mice are likely due to an impairment of both, the T cell and the B cell response." (PMID 39392861, 2024). "The acute infection phase, which lasts between four and eight weeks after transmission, is characterized by a rapid increase in viral load and a subsequent decline in CD4+ T cells." (PMID 39062562, 2024). "They represent another subset of CD4 T cells different from Th1 and Th2, which contributes to the inflammatory response and to the resistance to infection through diverse effector functions, depending on the pathogen." (PMID 38410517, 2024). "From EXP-CD4-HIV-Infection, we identified 274 DEGs in naive CD4+ T cell samples (192 up-regulated and 82 down-regulated), and 152 DEGs in central memory CD4+ T cell samples (119 up-regulated and 33 down-regulated)." (PMID 39519306, 2024). "A childhood infection supplies a large concentration of Ag to naïve B cells for the development of memory B cells, as well as generating memory CD4+ and CD8+ T cells specific to the infecting strain’s Ags." (PMID 38675771, 2024). "We show that cytomegalovirus (CMV) induces a population of unique memory CD4 T cells that expand late during infection and resolve viral persistence much better than conventional T memory cells." (PMID 38236791, 2024). "Recent studies have shown that both basophils and mast cells capture HIV and promote trans-infection of CD4+ T cells through interaction with four proteins (gp120, gp41, Tat, and Nef)." (PMID 39768136, 2024). "We classified these two participants as long-term infection cases due to CD4 cell counts and previous use of antiretroviral treatment." (PMID 39417513, 2024). "To explore the factors that condition the altered immunoglobulin profile in HEU infants, we analyzed the antibody profile of HEU infants according to maternal HIV viral load, CD4 count, concomitant infections, and ART treatments." (PMID 38375063, 2024). "For HA-specific CD4+ T cell responses measured against H5 by Lee and colleagues in the natural infection UK/Vietnamese study, T cell epitopes were identified in three regions of the HA stalk." (PMID 38805853, 2024). "We did detect a decrease in CCR4+CD4+ memory T cells at week 21 after infection in both the HTLV-1WT- and HTL-1p12KO-infected animals even after the re-depletion of NK cells, CD8+ cells, and monocytes." (PMID 38668247, 2024). "A previous study in the Kayseri region of Turkey detected T cell memory such as CD4 T cell response in humans after several years of infection." (PMID 39473598, 2024). "We quantified HIV-1 DNA within 91% of participants and infectious virus was recovered from 45% of participants indicating a high prevalence of in vivo infection despite low frequencies of circulating CD4+Vδ1 T cells." (PMID 39149467, 2024). "During infection with a type 1 immune response-inducing pathogen, activation of naïve pathogen-specific CD4+ T cells results in their differentiation into two major effector cell states: TH1 cells and TFH cells." (PMID 39321257, 2024). "After PR8-HA-GP61-80 infection, rGP immunization-induced memory CD4+ T cells preferentially gave rise to FR4+LY6C– Tfh-like secondary effector cells, whereas LCMV-induced memory T cells gave rise to FR4–LY6C+ Th1-like secondary effector cells." (PMID 39283916, 2024). "Age, calendar year of infection, CD4+ cell count nadir, ART virological failure, and HBcAb status were considered." (PMID 38543714, 2024).
infection (continued). "At 60 days post‐infection, these mice also showed increased frequencies of CD4+ T cells with activation (CD25+, CD69+ CD25+) and effector memory (KLRG1+) markers in the lungs." (PMID 39039808, 2024). "HK-fbp1 immunization was unable to protect mice from Cn-H99 infection in mice depleted of both CD4+ and CD8+ T cells, but mice with either CD4+ or CD8 T+ cells were fully protected." (PMID 39324785, 2024). "Several maternal factors, including viral load, CD4 count, concomitant infections, and ART, affect the immunological status of HEUs." (PMID 38375063, 2024). "We then investigated the impact of heterologous infection or immunization priming of CD4+ T cells on GC B cells in the lung." (PMID 39283916, 2024). "This pooled gRNA library was transduced at low multiplicity of infection (MOI) into primary CD4+ T cells previously selected for CBh-ZIM3-dCas9 expression." (PMID 38308274, 2024). "Upon recognition of pathogens by MHC II, CD4+ T cells produce antibodies that recruit other immune cells to the site of infection, thereby eliminating the pathogen." (PMID 39146923, 2024). "In summary, late-rising M09 CD4 T cells both resolve viral persistence during natural infection and protect better in vaccination, likely due to their unique phenotype and effector functions as compared to conventional memory CD4 T cell responses." (PMID 38236791, 2024). "Some studies revealed that TEM and TCM subsets of SARS-CoV-2–specific CD4+ T cells were induced after the infection, and the population can remain over half a year." (PMID 38533494, 2024). "At day 39 post-infection or -immunization, memory I-Ab:gp66-77 tetramer+ CD4+ T cells were detected in draining lymph nodes and spleens in both the GP(1°) and LCMV(1°) groups." (PMID 39283916, 2024). "Our long-term protection against infections depends in part on the maintenance of diverse populations of memory CD4 T cells, which are made in response to the initial exposure to the pathogen or a vaccine." (PMID 38948729, 2024). "The rate of infection was determined by quantifying the intracellular levels of p24-gag in CD4+ T cells." (PMID 39380908, 2024). "Further highlighting the importance of entry pathway to Lv3 restriction, productive infection of these rhesus macaque CMMT/CD4 cells by restricted HIV-1 can be rescued by overexpression of the human co-receptor (CXCR4 or CCR5)." (PMID 38497663, 2024). "Viral entry using the receptor CD4 antigen ensures productive infection when the T-lymphocytes are activated." (PMID 39810915, 2024). "Polyfunctional CD4 and CD8 T cells are associated with enhanced protective immunity during infections and vaccinations." (PMID 38271477, 2024). "The aim of this study was to distinguish CD4+ T cell responses in pre-patent and patent periods of infection to different preparations of filarial worm extracts." (PMID 39436444, 2024). "For example, IAV-specific CD4 Trm activation by viral antigen initiates a rapid inflammatory burst in the lungs, resulting in the control of viral titers within 40 hours of infection." (PMID 39688906, 2024). "Altogether, the controlled infection enabled us to map the dynamic changes of CD4+T cells in detail." (PMID 39013877, 2024). "To achieve a functional cure, we developed a strategy that constitutes mechanisms that protect CD4 T cells from infection to enable robust immune responses and thereby reducing the viral burden." (PMID 38808136, 2024). "The viral entry via CD4 into the yet-to-be activated resting T-cells can reportedly lead to productive infection with replication cycles with the caveat that functional P-TEFb expression is a requirement in these CD4+CD25− cells." (PMID 39810915, 2024). "CD4 modelling has been credited as a reliable method of producing an estimate of time of infection and as such, estimates from these papers are considered as the most reliable in this review." (PMID 38425215, 2024).
infection (continued). "Serum IFN-γ in nearly all sheep declined to pre-infection levels except for two CD4+ (#19/23) and one CD8+ (#25) T cell-depleted sheep, which had detectable IFN-γ levels of 5.122 ng/ml, 2.366 ng/ml, and 1.253 ng/ml, respectively, at 20 dpi." (PMID 38357545, 2024). "The binding of the Fv domain effectively impedes the attachment of HIV-1 to CD4+ cells, thus inhibiting viral entry and subsequent infection of host cells." (PMID 38932203, 2024). "Together, these data demonstrate that RACK1 is required for P. yoelii-primed activation and expansion of CD4+ T cells, and exerts a beneficial effect on Th1, Th17, and nTreg cell expansion during the early phase of infection." (PMID 39024388, 2024). "Despite the loss of CD4+ T cells, both coinfected animals successfully cleared SARS-CoV-2, suggesting the involvement of innate immune mechanisms in controlling the infection." (PMID 39066335, 2024). "While a significant increase in CD8+ T cells was also observed following vaccination and infection, it was notably less than the increase in CD4+ T cells." (PMID 38712080, 2024). "We have tried to estimate intervals between infection and diagnosis, and the proportions of foreign persons infected after their arrival in French Guiana based on CD4 erosion models." (PMID 39691355, 2024). "This will facilitate future studies with larger sample size to further address the lack of correlation between vaccine-induced neutralizing antibodies and CD4 T cells among previously infected individuals, and implications for further breakthrough infections." (PMID 38594497, 2024). "Upon infection by an antigen, antigen-specific naive CD4+ T cells become activated, undergoing rapid proliferation and differentiation into memory T cells and effector T cells." (PMID 39766817, 2024). "Specifically, type I interferons (IFNs) and NK cells play crucial roles during early infection, and CD8 and CD4 T cells play crucial roles during the late phase of acute infection." (PMID 39134803, 2024). "In myeloid cells obtained ex-vivo from dermal tissues, CD169-dependent binding to HIV-1 and trans-infection of CD4+ T cells have been observed, particularly in MDMs, but also partially in MDDCs." (PMID 39867902, 2024). "Prior to infection, there is a paucity of immune cells in the human kidney; most of these are CD4+ and CD8+ T cells, with a smaller percentage of NK cells, B cells, and CD14+, CD16+ and CD68+ myeloid cells." (PMID 40012912, 2024). "The aim of this paragraph is to highlight the differences and specificities of the different steps in and restrictions on the HIV-1 life cycle in macrophages, compared to the infection of CD4+ T cells." (PMID 38400063, 2024). "Conventional antiviral memory CD4 T cells typically arise during the first two weeks of acute infection." (PMID 38236791, 2024). "Upon Mtb infection of naive mice, initial accumulation of activated CD4+ T cells in the lung is delayed, occurring between 2–3 weeks post-infection." (PMID 38922679, 2024). "This differential expression pattern suggests a potential role for Integrin α4 in the differentiation, functional specialization, or migratory behavior of these CD4 T cell subsets during the immune response to LCMVArm infection." (PMID 39720725, 2024). "Qualitatively, our findings were consistent across transmitter allocation methods and when log10 SpVL and CD4+ T cell decline were compared with the probability that infection is initiated by multiple particles (pages S20 and S21)." (PMID 39471873, 2024). "This lifelong HIV latent reservoir is quickly established in vivo after infection and primarily consists of memory resting CD4 T cells harboring the viral genome integrated into their DNA4,5." (PMID 38886484, 2024). "Cellular immune responses, including CD4+ and CD8+ T cell responses, play a crucial role in protecting against different SARS-CoV-2 variants infection." (PMID 38533494, 2024).